CD44 (CD44 molecule (IN blood group))
Diseases named in the same sentence as CD44 in open-access papers (continued):
Sharing a sentence is not in itself a finding about the gene and the disease.
hepatocellular carcinoma (continued). "Additionally, it has been found miR-199a/b-3p can inhibit HCC growth, apoptosis, invasion and angiogenesis via multiple targets, such as PDCD4, CD44, CD151, VEGFA AEGFR1/2, HGF and MMP235–38 and can affect the chemical sensitivity of hepatoma cells to doxorubicin via mTOR and c-Met39." (PMID 38168113, 2024). "However, the Cd44 gene status had no influence on either the number of primary liver tumors detected or on the level of the hepatocellular carcinoma biomarker AFP (α-fetoprotein) in the serum of Nf2-mutant mice." (PMID 37174657, 2023). "CD44, a cancer stem cell (CSC) marker, is required for maintaining CSC properties in hepatocellular carcinoma (HCC)." (PMID 32168951, 2020). "In hepatocellular carcinoma (HCC), cell membrane proteins such as CD133, CD13, CD90, EpCAM and CD44 have been widely applied to isolate different types of hepatic cancer stem cells (hCSCs)." (PMID 26571119, 2015). "CD44, being one of the most commonly used CSC markers in hepatocellular carcinoma (HCC), has been demonstrated to act as a multidomain, transmembrane platform that serves to integrate a wide variety of extracellular signals." (PMID 25797261, 2015). "Although the regulation of CD44 expression in hepatocellular carcinoma is not completely understood, recent studies have revealed that the increased CD44 expression in HCC is correlated with increased metastasis, recurrence, resistance to chemotherapy or radiation therapy, and decreased survival." (PMID 24971320, 2014). "The authors demonstrated that casticin reduced stemness characteristics in two lines of hepatocellular carcinoma (HCC), MHCC97H and SK-Hep-1, by reducing the CD44+ cell population, the CD44 protein levels, and the expression of stemness biomarkers EpCAM, Bmi, Nanog, and Oct4 mRNAs." (PMID 37304067, 2023). "In hepatocellular carcinoma (HCC), 71.4% of HCC patients were CTC positive for the cancer stem cell marker, CD44; thus, they had a significant population of CTCs with stem properties, which could contribute to tumor cell survival and dissemination." (PMID 34803167, 2021). "In patients with hepatocellular carcinoma (HCC) recurrence, the majority of hepatic stem/progenitor cell (HSC/HPC) biomarkers are overexpressed, including cytokeratin 19, ABCG2, CD133, Nestin, and CD44, and angiogenesis agents CD34, VEGF, and PD-ECGF." (PMID 32466488, 2020). "Similarly, in alpha-fetoprotein-negative hepatocellular carcinoma (AFP-negative HCC), both SPP1+ TAMs and CD44 expression on T cells and tumor cells are highly enriched." (PMID 41425545, 2025). "Cells that meet the four indexes of CD133+, CD44+, CD24+, and EpCAM+ are defined as human liver cancer stem cells (hLCSCs), and cells that satisfy the four indexes of CD133-, CD44-, CD24-, and EpCAM are defined as non-hepatoma stem cells (non-hLCSCs)." (PMID 31900225, 2020).
bladder cancer (140 papers, 2004 to 2026). "Recent studies have indicated the close association of CD44 with the metastatic ability and stemness of bladder cancer cells." (PMID 40011711, 2025). "Transcriptomics analysis has revealed significant heterogeneity among CD44 isoforms in 75 patients with bladder cancer, which is thought to be associated with tumor invasion and poor prognosis." (PMID 39132499, 2024). "In bladder cancer CD44 expression on the surface of cells is associated with a more aggressive cellular phenotype and has been used to stratify patient prognosis." (PMID 38539529, 2024). "The transmembrane receptor CD44, known for its affinity to hyaluronic acid, has been implicated in facilitating tumor growth and metastasis, including in the context of bladder cancer." (PMID 38339238, 2024). "This study also found that CD44 expression in bladder cancer patient samples was significantly associated with tumor infiltration by immune cells." (PMID 38539529, 2024). "This review will discuss the relationship between CD44 and bladder cancer biology and patient outcome and its utility as a diagnostic, prognostic, and predictive marker." (PMID 38539529, 2024). "Results from a meta-analysis interrogating dataset of 33 cancer types from TCGA, revealed that CD44 expression is negatively associated with TMB in bladder cancer." (PMID 38600583, 2024). "There is a strong association between CD44 expression and bladder cancer clinical stage, lymph node metastasis, as well as disease-specific survival." (PMID 38539529, 2024). "Our findings, in conjunction with TCGA data, highlight that CD44 expression is linked to poorer outcomes in bladder cancer." (PMID 39768377, 2024). "Along with integrin subtypes, CD44 members are involved in the fate of tumor cells and are associated with bladder cancer size, tumor grade, and recurrence." (PMID 37835543, 2023). "High CD44 expression as a HA receptor is associated with a higher clinical stage, lower treatment response rates, and shorter survival rates in bladder cancer." (PMID 37111795, 2023). "For instance, CD44 is implicated in the development of cisplatin and radiation resistance in bladder cancer." (PMID 35740662, 2022). "Considering the prognosis, human and animal-based studies have shown CD44 upregulation in bladder cancer, where CD44 overexpression has been associated with the prognostically adverse muscle-invasive basal subtype of bladder cancer." (PMID 34884696, 2021). "Studies have shown that the overexpresseion of HAS1 in bladder cancer cells can cause an increase in the CD44 variant isoforms (HA receptor), thereby inhibite Fas mediated apoptosis, and promoting the growth and invasion of bladder cancer cells." (PMID 32596162, 2020). "High expression of CD44 has been associated with higher clinical stage and aggressiveness in bladder cancer." (PMID 32922663, 2020). "A serial of studies demonstrate that the onset and progression of bladder cancer are closely associated with multiple gene polymorphisms including CD44, XRCC1, and PDCD6." (PMID 30755233, 2019). "Today, the role of genetic factors in the incidence of bladder cancer has attracted widespread attention and several genes are currently associated with the incidence of bladder cancer, including CD44, CRCC1, and PDCD6." (PMID 30755233, 2019). "Similar observations were made in bladder cancer cells in which silencing of HAS1 suppressed the level of CD44 variant isoforms." (PMID 28460475, 2017). "In bladder cancer, the surface markers CD44 and CD49f have been implicated in the cancer-initiating population important in cancer self-renewal and repopulation." (PMID 28487492, 2017). "Particularly, both CD44 and its splicing variants have been involved in bladder cancer carcinogenesis and progression." (PMID 29207682, 2017). "Since loss of either CD44 or RHAMM induced apoptosis in the two different shAGL bladder cancer cells (UMUC3 and T24T respectively) used, we decided to include a third cell line into our study." (PMID 27595989, 2016).
bladder cancer (continued). "TUNEL staining showed more apoptotic cells with loss of HAS2, CD44 or RHAMM in AGL low bladder cancer cells." (PMID 27595989, 2016). "We identified that loss of either CD44 or RHAMM induce apoptosis in specific low AGL bladder cancer cell lines." (PMID 27595989, 2016). "Detailed investigation is required to understand how death receptor signaling and apoptosis is triggered by either CD44 or RHAMM knockdown in rapid growing bladder cancer cells driven by AGL loss." (PMID 27595989, 2016). "Another stemness marker, CD44, has been identified as a cell surface marker associated with cancer stem cells in tumors, including urinary bladder cancer." (PMID 28050219, 2016). "We observed loss of either CD44 or RHAMM is important for induction of apoptosis in specific AGL low bladder cancer cell line." (PMID 27595989, 2016). "These outcomes illustrate that specific AGL knockdown bladder cancer cell lines undergo apoptosis with inhibition of either CD44 or RHAMM and loss of this particular HA receptor also inhibit HA synthesis by a feedback mechanism." (PMID 27595989, 2016). "The analysis of CD44 isoforms in invasive bladder cancer cells CD44 is largely divided into CD44 standard isoform and variant isoforms, exclusively expressed in mesenchymal cells and epithelial cells, respectively." (PMID 25551284, 2014). "This novel miR-34a/CD44/EMT related factor provides new insight into the mechanisms underlying tumor metastasis in bladder cancer." (PMID 25551284, 2014). "Another stemness marker, CD44, has been identified as a cell surface marker associated with cancer stem cells in several types of tumors, including urinary bladder cancer." (PMID 24382987, 2013). "Expression of CD44v6, a splicing variant of CD44, is correlated with proliferation of poorly differentiated urothelial cells and the characteristic phenotype of tumor-initiating bladder cancer stem cells." (PMID 24382987, 2013). "CD44 is a receptor for hyaluronic acid, and its variant isoform 6 (CD44v6) is a molecular marker for bladder cancer." (PMID 22577245, 2012). "CD44 has been identified as a cell surface marker associated with cancer stem cells in several types of tumors including urinary bladder cancer." (PMID 22577245, 2012). "However, bladder cancer stem cells are highly resistant to chemotherapeutic drugs, and the expression of CD44 standard length and the CD44v6 isoform are commonly associated with bladder cancer stem cells." (PMID 38539529, 2024). "However, it should be noted that correlation of CD44 isoforms with bladder cancer clinical outcome associations requires further validation." (PMID 38539529, 2024). "CD44 expression is associated with bladder cancer aggressiveness and resistance to chemo and radio treatment, and the ratio in urothelial cancer tissue and urinary exfoliated cells showed a significant correlation in the same patients; therefore, it was proposed as a prognostic predictor." (PMID 38255201, 2024). "For example, by siRNA-mediated silencing of GALNT1, which control O-linked glycosylation activation of SHH signaling in CD44+ CSCs in bladder cancer to mediate stemness, the tumor growth was suppressed in a similar extent to cyclopamine in an orthotopic mouse model of bladder cancer." (PMID 33889547, 2021). "We further analyzed whether CD44 expression was linked to the clinicopathological characteristics of patients with bladder cancer." (PMID 32434417, 2020). "OPN signaling via CD44 has been implicated in the metastasis of bladder cancer cells." (PMID 33203146, 2020). "Moreover, in bladder cancer, the downregulation of CD44 variant caused due to a decrease in HA production had a regulatory role in cell growth and apoptosis." (PMID 32582701, 2020). "Interestingly loss of either CD44 or RHAMM induces apoptosis in different low AGL expressing bladder cancer cell lines." (PMID 27595989, 2016).
bladder cancer (continued). "Since loss of HAS2 induced apoptosis predominantly in the rapid growing shAGL bladder cancer cells we decided to investigate whether loss of the two dominant HA receptor CD44 and RHAMM, result in similar apoptotic induction of shAGL bladder cancer cells." (PMID 27595989, 2016). "Moreover knockdown of HAS2, CD44 and RHAMM reduced growth and induced apoptosis predominantly in the AGL knockdown bladder cancer cells confirming that loss of AGL drives bladder cancer growth via HAS2/HA/CD44-RHAMM axis." (PMID 27595989, 2016). "In a case—control study of bladder cancer-associated biomarkers, voided urine samples from 127 subjects, 64 with bladder cancer patients and 63 controls, were examined, and the urine concentrations of four different biomarkers, including the CD44 protein, were assessed via ELISA." (PMID 41440277, 2025). "Thus, the mean and median urinary levels of CD44 are negatively associated with bladder cancer." (PMID 41440277, 2025). "The identification of osteopontin (OPN) as a ligand for CD44 was made in 1997 and has been implicated in a number of physiological and pathological conditions including metastasis of nasopharyngeal carcinoma and bladder cancer, as well as control of CD8+ T cell activation and tumor immune evasion." (PMID 38539529, 2024). "Therefore, we propose that CD44 specifically recognized by KMP1 might undergo O‐linked glycosylation mediated by ppGalNAc T1 in bladder cancer." (PMID 29577645, 2018). "For example, the expression of stem cell markers such as SOX2, IGF1R, SOX4, ALDH1, and CD44 affects the likelihood of recurrence and metastasis in bladder cancer." (PMID 41153362, 2025). "Meanwhile, AR activation was shown to reduce the expression of CD44 known to involve cell-cell interactions and cell adhesion/migration, suggesting the protective role of AR in bladder cancer." (PMID 40486871, 2025). "Analysis of tissue samples from 300 bladder cancer patients revealed that CD44+ cells made up approximately 40% of all tumor cells." (PMID 40635786, 2025). "A recent review discussed the role of CD44-expressing cells in bladder cancer and positioned CD44 as a promising biomarker and therapeutic target for noninvasive diagnosis and innovative treatments." (PMID 41440277, 2025). "Urinary CD44 levels were positively correlated with high-grade bladder cancer compared with both control subjects and patients with low-grade tumors." (PMID 41440277, 2025). "For bladder cancer, HA-based clinical applications include conjugating chemotherapeutic agents to HA, thereby allowing cells with high levels of HA receptors, such as CD44, to uptake the agents." (PMID 38539529, 2024). "These same facts make CD44 a strong therapeutic target in many cancer types, including bladder cancer." (PMID 38539529, 2024). "Elevated CD44 expression has also been observed in exosomes from bladder cancer cells, supporting its utility as a tumor biomarker." (PMID 39766023, 2024). "The study’s authors identified CD44 among a six gene panel, which had high prognostic value relating to the overall survival of bladder cancer patients." (PMID 38539529, 2024). "In fact, CD44 was found to be one of the main differentially expressed genes between bladder cancer patients and control urine samples." (PMID 38539529, 2024). "A PTX-HA formulation, namely ONCOFID-P-BTM, has been reported to significantly increase CD44-dependent cellular uptake of the chemotherapy moiety in bladder cancer cell lines." (PMID 38600583, 2024). "CD44 has been identified as a protein which is strongly correlated with disease state in bladder cancer." (PMID 38539529, 2024). "There are several therapeutics being developed that take advantage of CD44 protein levels commonly being higher in bladder cancer compared to normal urothelium and that CD44 is a receptor for HA." (PMID 38539529, 2024).
bladder cancer (continued). "In human patients with bladder cancer, tumor AR, CD44 mRNA, and protein expression were inversely correlated, suggesting a clinically relevant AR–CD44 axis." (PMID 38539529, 2024). "While the existing data is supportive of CD44 playing a significant role in cancer progression and response rates to ICIs, including bladder cancers, the mechanistic details behind this role remain limited." (PMID 38539529, 2024). "For instance, miR‐204/CD44 axis, miR‐1247‐3p/FOXO1 axis, and miR‐26a‐5p/SLC7A11 axis have been implicated in NSCLC, bladder cancer, and OSCC, respectively." (PMID 39177014, 2024). "Third, the levels of CD44 can be assessed in urine voided from bladder cancer patients, possibly informing on the aggressiveness or stage of the cancer without the need for invasive testing." (PMID 38539529, 2024). "CD44 has been found to have a relationship with the male hormone androgen and its receptor in bladder cancer." (PMID 38539529, 2024). "Targeting the CD44 protein itself has shown promise to counter the growth of bladder cancer cells in vitro and in mouse models." (PMID 38539529, 2024). "All told, multiple studies have found CD44 to correlate with bladder cancer presence when examining this in urine, highlighting the importance of this protein, and its expression levels, in diagnostic methods for bladder cancer." (PMID 38539529, 2024). "CD44, a cell surface glycoprotein, has been extensively studied as a marker of bladder cancer aggressiveness and stemness." (PMID 39132499, 2024). "Cytokeratin 14 (KRT-14), aldehyde dehydrogenase 1a (ALDH1a), and the transcription factors SOX2 and CD44 have been shown to initiate bladder cancer." (PMID 38607066, 2024). "The ISO attenuated CD44 expression results inhibition of stem cell-like properties and invasion of bladder cancer cells." (PMID 38462600, 2024). "Another use of CD44 as a marker is to define cellular subtypes in bladder cancer, which has been shown to stratify patient prognosis and therapeutic response in muscle-invasive disease." (PMID 38539529, 2024). "Secondly, in this study, the CD44+ALDH1A1+ subpopulation was referred to as bladder cancer stem-like cells, which is consistent with a previous study." (PMID 38191448, 2024). "Progression-free survival of bladder cancer patients was also shown to correlate with expression levels of CD44 in patient urine." (PMID 38539529, 2024). "In this study, macrophage-secreted osteopontin was found to bind to a short version of CD44 (CD44s) on the tumor cells and promote bladder cancer invasion and growth." (PMID 38539529, 2024). "CD44 is widely used as a bladder cancer stem cells biomarker, and interference of CD44 expression inhibits stemness and progression in bladder cancer cells." (PMID 38462600, 2024). "Elevated expression of CD44 was reported on bladder cancer tissue samples, primary cells, cell lines, and organoids." (PMID 37626918, 2023). "A combined NANOG and CD44 expression were identified as independent prognostic biomarkers for recurrence-free survival and overall survival in bladder cancer." (PMID 37627900, 2023). "We found that patients with bladder cancer with high CD44 expression had worse survival than those with low CD44 expression (P < 0.05)." (PMID 37316699, 2023). "In order to further explore the pathway mechanism of CD44 and bladder cancer, KEGG pathway analysis was carried out by Metascape." (PMID 37316699, 2023). "An inhomogeneous response from the bladder cancer cell lines to the mistletoe extracts was also apparent in regard to CD44 expression." (PMID 37835543, 2023). "This is the first report identifying integrin adhesion receptors and CD44 as targets of mistletoe extracts relevant for modulating the growth and proliferation of bladder cancer cells." (PMID 37835543, 2023). "We report the original study of CD44 expression in human bladder cancer and its relationship to tumorigenesis." (PMID 37316699, 2023).